DNAAF1 (dynein axonemal assembly factor 1)
Description:
Cilium-specific protein required for the stability of the ciliary architecture. Plays a role in cytoplasmic preassembly of dynein arms. Involved in regulation of microtubule-based cilia and actin-based brush border microvilli.
Synonyms: LRRC50; FLJ25330; ODA7; CILD13; swt; DAU1
Tractability: Antibody: its Gene Ontology location is reachable by antibodies, with medium confidence. PROTAC: its protein half-life has been measured.
Gene: Protein-coding gene on chromosome 16 (84,145,261 to 84,178,769, forward strand). Ensembl gene ENSG00000154099.
Subcellular location: Cell projection, cilium; Cytoplasm; Cytoplasm, cytoskeleton, spindle pole
Gene Ontology:
Molecular function: dynein complex binding
Biological process: axonemal dynein complex assembly; cilium assembly; cilium movement; determination of digestive tract left/right asymmetry; determination of liver left/right asymmetry; determination of pancreatic left/right asymmetry; heart looping; inner dynein arm assembly; left/right pattern formation; lung development; motile cilium assembly; outer dynein arm assembly; regulation of cilium beat frequency; axoneme assembly; determination of left/right symmetry; epithelial cilium movement involved in determination of left/right asymmetry
Cellular component: axoneme; cytoplasm; cilium; extracellular region; spindle pole
Genetic constraint (gnomAD): Loss-of-function variants: 66 observed, 71.37 expected, observed/expected ratio (o/e) 0.92, 90% interval 0.76 to 1.13. The upper end of that interval is the gene's LOEUF score, 1.13, which puts it in group 4 of 6, group 1 being the genes least tolerant of losing a copy. Missense variants: 1,173 observed, 920.87 expected, observed/expected ratio (o/e) 1.27, 90% interval 1.21 to 1.34. Synonymous variants: 414 observed, 366.97 expected, observed/expected ratio (o/e) 1.13, 90% interval 1.04 to 1.22.
Gene-disease validity (ClinGen):
ClinGen rates the evidence that DNAAF1 causes each of these diseases.
primary ciliary dyskinesia 13 (autosomal recessive): Definitive.
Homologues: Orthologues: chimpanzee DNAAF1 (98% identical), macaque DNAAF1 (86% identical), pig DNAAF1 (60% identical), dog DNAAF1 (60% identical), mouse Dnaaf1 (55% identical), guinea pig DNAAF1 (55% identical), rat Dnaaf1 (55% identical), tropical clawed frog dnaaf1 (36% identical), zebrafish dnaaf1 (30% identical), Drosophila melanogaster dtr (29% identical). Paralogues in human: LRRC9 (15% identical), LRGUK (14% identical), LRRCC1 (13% identical), CEP97 (12% identical), DRC3 (12% identical), LRRC43 (12% identical), LRRC49 (11% identical), DNAAF11 (10% identical), PPP1R42 (9% identical), LRRC46 (8% identical), LRRIQ3 (8% identical), LRRC23 (8% identical), and 1 more.
Diseases named in the same sentence as DNAAF1 in open-access papers:
DNAAF1 is named in the same sentence as 34 diseases in open-access papers, as found by Europe PMC text mining. Sharing a sentence is not in itself a finding about the gene and the disease. The quoted sentences say what the papers report.
primary ciliary dyskinesia (7 papers, 2016 to 2025). A rare, genetically heterogeneous, primarily respiratory disorder characterized by chronic upper and lower respiratory tract disease. "Mutations in DNAAF1 are linked to tissue asymmetry development and primary ciliary dyskinesia (PCD)." (PMID 33251213, 2020). "DNAAF1 (LRRC50) is a cytoplasmic protein required for dynein heavy chain assembly and cilia motility, and DNAAF1 mutations cause primary ciliary dyskinesia (PCD; MIM 613193)." (PMID 29228333, 2018). "Previous studies showed that mutations in the motile cilia gene DNAAF1 cause primary ciliary dyskinesia and seminoma." (PMID 27543293, 2016). "Dnaaf1, also known as Lrrc50 (Leucine-rich repeat-containing protein 50) or Oda7 (Outer dynein arm 7), is important for ciliary beat frequency in Chlamydomonas reinhardtii and a causal gene for primary ciliary dyskinesia (PCD) in humans." (PMID 27261005, 2016). "DNAAF1 is the prototype of the motile cilia protein because it takes part in the assembly and stability of the outer and inner dynein arm of motile cilia; mutations of DNAAF1 cause primary ciliary dyskinesia-13." (PMID 30149579, 2018).
Hydrocephalus (5 papers, 2016 to 2025). Hydrocephalus is an active distension of the ventricular system of the brain resulting from inadequate passage of CSF from its point of production within the cerebral ventricles to its point of absorption into the systemic circulation. "All nine cases with different DNAAF1 mutations presented varying clinical features of NTDs, e.g., anencephaly, meningomyelocele, varying degrees of spina bifida, and hydrocephalus." (PMID 27543293, 2016). "In particular, consistent with previous conclusions that hydrocephalus is a very common association with spina bifida, four out of the nine patients affected by spina bifida also displayed hydrocephalus, suggesting that variants in DNAAF1 might be associated with NTDs." (PMID 27543293, 2016). "DNAAF1 is a key structure gene of the motile cilia, but very little information had been reported on motile cilia and neural tube development, except for their occasional roles in the formation of the hydrocephalus." (PMID 27543293, 2016). "Importantly, the histologically-confirmed hydrocephalus phenotype has remained 100% concordant with homozygosity for the mutations in Dnaaf1 (N = 12) and Lrrc48 (N = 16), and we have never observed hydrocephalus in mice that are not homozygous at these loci (N > 100 for both lines)." (PMID 27261005, 2016). "Moreover, hydrocephalus is frequently observed across murine motile-cilia gene knockouts (e.g., DNAH5, DNAAF1) but remains uncommon in human PCD except in rare ciliogenesis disorders (e.g., CCNO, FOXJ1), underscoring a rodent–human discrepancy." (PMID 41477643, 2025).
seminoma (5 papers, 2013 to 2016). A radiosensitive malignant germ cell tumor found in the testis (especially undescended), and extragonadal sites (anterior mediastinum and pineal gland). "Intriguingly all of the five cases we identified with rare germline DNAAF1 mutation had either seminoma (n=4) or mixed histology (n=1)." (PMID 27996046, 2016). "Collectively these data are consistent with loss of DNAAF1 having a more general impact on seminoma oncogenesis." (PMID 27996046, 2016). "In addition DNAAF1 is highly methylated in seminomas, as compared with non-seminomas (P=2.3 × 10−7, Kruskal–Wallis test), and this is accompanied by downregulation of DNAAF1 expression as compared with normal testis (P=2.2 × 10−16, Kruskal–Wallis test)." (PMID 27996046, 2016). "DNAAF1 mutations have been found in PCD patients with or without situs inversus and seminoma patients." (PMID 27261005, 2016). "Here, we describe the susceptibility to tumor formation of heterozygous lrrc50Hu255h zebrafish and suggest a tumor suppressor role for LRRC50 (alias DNAAF1; dynein assembly factor 1) in the specific development of the TGCT subtype seminoma in both zebrafish and man." (PMID 23599692, 2013).
Infertility (4 papers, 2013 to 2023). "But absolute infertility is occurred in female with mutations in the genes DNAAF1 and LRRC6 encoding dynein axonemal assembly factor." (PMID 36583018, 2022). "These genes play important roles in cell proliferation (RFX4, FOXM1, ASF1B), differentiation during spermatogenesis (CATSPERG, SPDYA, SPATA16, TSACC, TCP10L, DPY19L2) and motility of sperm cells during fertilization (DNAAF1); mutations in these genes may lead to infertility." (PMID 31671693, 2019).
ciliopathy (3 papers, 2013 to 2022). A genetic disorder of the cellular cilia or the cilia anchoring structures, the basal bodies, or of ciliary function. "Finally, several factors related to ciliopathies such as DNALI1, DNAAF1, CCDC65, CCDC39, and LRRC34 were strongly reduced already at P17 (14–31% of wild-type level)." (PMID 36611846, 2022).
male infertility (3 papers, 2016 to 2025). The inability of the male to effect fertilization of an ovum after a specified period of unprotected intercourse. "Five other dynein preassembly genes (DNAAF1, DNAAF3, DNAAF5, SPAG1, and CFAP298 (C21orf59)) are known to be associated with PCD and putatively, male infertility." (PMID 33635866, 2021).
scoliosis (2 papers, 2020 to 2024). A congenital or acquired spinal deformity characterized by lateral curvature of the spine. "In particular, we identified the dynein-associated gene Dnaaf1, which is known to cause scoliosis in zebrafish, to be downregulated in Xe1+PEC7 compared to Xe1 female KO P2 tails." (PMID 38461417, 2024).
anencephaly (1 paper, 2016). A rare neural tube defect during pregnancy, resulting in the absence of a large portion of the brain and skull in the fetus. "DNAAF1 frameshift mutation p.Gln341Argfs*10 (c.1022_1023delAA) was identified in a male fetus (A1431) at 17 wk gestation, affected by anencephaly and meningomyelocele, two typical NTD phenotypes." (PMID 27543293, 2016).
congenital heart disease (1 paper, 2018). A heart disease that is present at birth. "This identified putative disease-causing mutations in DNAAF1 in four families with complex congenital heart disease, with or without a clinical diagnosis of PCD." (PMID 29228333, 2018).
immunodeficient diseases (1 paper, 2022). "The functional capacities of the highly expressed DEGs in the Chinese Simmental cattle mainly focused on inflammatory diseases (CXCL9 and FCRL1), immunodeficient diseases (ADM2, CCL5, and CAMKV), carcinoma (CXCL11, JAKMIP2, GZM, and DNAAF1), and GTP binding and GTPase activity (NUGGC)." (PMID 35495650, 2022).
meningoencephalocele (1 paper, 2016). A congenital abnormality in which the meninges protrude through a defect in the cranium. "A 5-yr-old female patient (SY656) carrying the DNAAF1 p.Ala685Val (c.2054C > T) variant also presented with meningoencephalocele." (PMID 27543293, 2016). "The DNAAF1 p.Asn124Ser (c.371A > G) substitution was found in a male fetus (SY657) with meningoencephalocele at 36 wk gestation." (PMID 27543293, 2016).
Obesity (1 paper, 2014). Accumulation of substantial excess body fat. "The DNAAF1 gene is required for the stability of the ciliary architecture, and it has been demonstrated that ciliary dysfunction is associated with the pathogenesis of obesity." (PMID 25158045, 2014). "In addition, we identified a sequence variant in the DNAAF1 gene that might be implicated in the development of severe obesity associated with ciliary dysfunction." (PMID 25158045, 2014). "However, it is possible that identified DNAAF1 sequence variants are causing a milder form of PCD with recurrent airway infections and severe obesity." (PMID 25158045, 2014). "A comprehensive bioinformatics analysis found de novo and compound heterozygote sequence variants with a damaging effect on genes previously associated with obesity in mice (LRP2) and humans (UCP2), among other intriguing mutations affecting ciliary function (DNAAF1)." (PMID 25158045, 2014).
Situs inversus totalis (1 paper, 2025). "Individual 109, a descendant of a consanguineous family, presented with situs inversus totalis, carried biallelic frameshift variants in DNAAF1 (c.1228_1232delCCAGA; p.Pro410fs*8) and had respiratory epithelial cells that were were almost immotile." (PMID 40142748, 2025). "Individual 9, a descendant of a consanguineous family, presenting with situs inversus totalis, carried biallelic missense variants in DNAAF1 (c.1385A>C; p.Gln462Pro) and had respiratory epithelial cells displaying a minimal residual ciliary movement." (PMID 40142748, 2025).
tumor (7 papers, 2013 to 2022). "Immunohistochemistry (IHC) staining for DNAAF1 showed complete absence in 3/3 tumours available from DNAAF1 mutation carriers, with presence of the protein demonstrable in normal surrounding tissue." (PMID 27996046, 2016). "The most significantly mutated CMG is DNAAF1 with biallelic inactivation and loss of DNAAF1 expression shown in tumours from carriers." (PMID 27996046, 2016). "More than 40% of cancer susceptibility genes are found to be tumorigenic when mutated only in tumour DNA27, accordingly we sought to assess whether DNAAF1 was also frequently lost somatically." (PMID 27996046, 2016). "Collectively these findings are compatible with DNAAF1 having a tumour suppressor function." (PMID 27996046, 2016).
DNAAF1 also shares sentences with these, for which no sentence is quoted: cancer (3 papers); neural tube defect (2); chronic lung disease (1); head and neck cancer (1); idiopathic scoliosis (1); infection (1); Joubert syndrome (1); lung adenocarcinoma (1); lung carcinoma (1); Meningomyelocele (1); pituitary adenomas (1); Senior-Loken syndrome (1); sinusitis (1); situs inversus (1); spermatocytic seminoma (1); spina bifida (1); squamous cell lung carcinoma (1); testicular germ cell tumor (1); testicular germ cell tumours (1); testicular tumors (1).